NOTCH1 (notch receptor 1)
Diseases named in the same sentence as NOTCH1 in open-access papers (continued):
Sharing a sentence is not in itself a finding about the gene and the disease.
laryngeal carcinoma (11 papers, 2018 to 2025). Carcinoma that arises from the laryngeal epithelium. "In particular, these upregulated genes were determined to have the potential to be small-molecule targets for precision therapy in patients who had recurrent laryngeal cancer with NOTCH1 mutations." (PMID 35911687, 2022). "In our study, the GSEA results obtained from an analysis the TCGA-laryngeal cancer dataset also showed that gene sets associated with B-cell active pathways were significantly downregulated in tumors with NOTCH1 mutations." (PMID 35911687, 2022). "Similarly, NOTCH1 expression has also been associated with worse overall survival in laryngeal cancer." (PMID 41009728, 2025). "Thus, to elucidate the role of NOTCH1 mutation on recurrence in resected laryngeal cancers, we further investigated the variation in the anti-tumor immunity of the TiME in relapsed tumors with NOTCH1 mutation and NOTCH1 wild-type tumors by Nano-String gene expression assay." (PMID 35911687, 2022). "For example, the silence of NOTCH1 in the laryngeal carcinoma Hep-2 cell line affects the migration and invasion and promotes metastasis." (PMID 40231252, 2025). "This study aimed to identify the effects of Notch1 signaling on proliferation and apoptosis of laryngeal cancer cells in a hypoxic microenvironment." (PMID 35982489, 2022). "The role of Notch1 signaling in regulating cellular proliferation and apoptosis in laryngeal carcinoma in Hep-2 cells in vitro is also controversial." (PMID 35982489, 2022). "Further research is needed to examine the molecular mechanisms by which Notch1 signaling regulates proliferation and apoptosis of human laryngeal carcinoma cells." (PMID 35982489, 2022). "Immunostaining for Notch1 was observed in 68 (63.55%) of 107 laryngeal cancer tissue samples and was located in the membrane and cytoplasm of tumor cells." (PMID 35982489, 2022). "The Cancer Genome Atlas (TCGA)-laryngeal cancer dataset also revealed weakened immune response and impaired adhesion functions in NOTCH1-mutant patients." (PMID 35911687, 2022). "LSCC samples from 107 laryngeal cancer patients were labeled for Notch1 by using immunohistochemistry." (PMID 35982489, 2022). "Notch1 signaling may play a pivotal role in regulating the proliferation and apoptosis resistance of laryngeal cancer cells under hypoxic conditions." (PMID 35982489, 2022). "Small interfering RNA (siRNA) was used to inhibit Notch1 expression in laryngeal cancer cells." (PMID 35982489, 2022). "Furthermore, our study indicated that Notch1 expression in laryngeal carcinoma tissues was negatively correlated with the AI and positively correlated with the PI, which further validates the conclusion of our in vitro study." (PMID 35982489, 2022). "Accordingly, the purpose of the current study was to further examine the effects of Notch1 signaling on the regulation of apoptosis and proliferation of laryngeal cancer cells in a hypoxic microenvironment to clarify the regulatory role of Notch1 signaling in tumor progression." (PMID 35982489, 2022). "We have previously reported that its overexpression in laryngeal cancer tissues was associated with a lower risk to develop regional lymph node metastases and that it reduced invasion and proliferation of laryngeal cancer cells in vitro likely through the dysregulation of NOTCH-1-dependent pathway." (PMID 34066893, 2021). "As the Notch1 signalling pathway could be suppressed by silencing SNHG1 in laryngeal cancer, our study aimed to explore the role of Notch1 in GC development." (PMID 32423385, 2020).
laryngeal carcinoma (continued). "In summary, current research demonstrates that Notch1 signaling may play a critical role in regulating proliferation and apoptosis of laryngeal cancer cells in the hypoxic microenvironment and may be an effective target for the treatment of laryngeal cancer." (PMID 35982489, 2022). "Thus, Notch1 signaling may contribute to the proliferation and apoptotic resistance of laryngeal cancer cells in a hypoxic microenvironment." (PMID 35982489, 2022). "Furthermore, we examined whether hypoxia was involved in regulating the activity of Notch1 signaling in laryngeal cancer cells, and the present study demonstrated that Notch1 expression and Notch1 signaling activity in Tu212 and AMC-HN-8 cells could be enhanced by hypoxia." (PMID 35982489, 2022). "The Western blot results demonstrated that the protein expression of Notch1 and N1ICD in laryngeal cancer cells was enhanced by hypoxia (P < 0.05)." (PMID 35982489, 2022). "Moreover, the authors silenced NOTCH1 in human laryngeal carcinoma HEp-2 cell line to elucidate the downstream effects on LSCC cell proliferation, apoptosis, migration, and invasion, demonstrating the contribution of NOTCH1 to the last two processes." (PMID 35406495, 2022).
lung squamous cell carcinoma (11 papers, 2013 to 2025). "As previously reported 27, Notch1 can enhance the migration and infiltration of circulating tumor cells in lung squamous cell carcinoma (LUSC)." (PMID 39991567, 2025). "SHAP analysis identified NOTCH1 as a novel predictive biomarker, whose feature contribution profile suggests a role in immune modulation in lung squamous cell carcinoma." (PMID 41488620, 2025). "In our preliminary studies, the expression of Notch1 in lung squamous cell carcinoma, adenocarcinoma and SCLC specimens was detected by immunohistochemical methods." (PMID 23420695, 2013). "Thus, it is plausible that NOTCH1 indirectly modulates PD-L1 expression in lung squamous cell carcinoma through these or related mechanisms, though this requires confirmation in future studies." (PMID 41488620, 2025). "In lung squamous cell carcinoma (LSCC), Notch1 and Dll4 are significantly lower than in other subtypes, with the exception of the adenocarcinomas, where Notch1 remains highly expressed." (PMID 32796631, 2020).
myocardial ischemia (11 papers, 2013 to 2025). A disorder of cardiac function caused by insufficient blood flow to the muscle tissue of the heart. "Notch1 signaling can attenuate myocardial ischemia/reperfusion injury by suppressing oxidative/nitrative stress." (PMID 35891967, 2022). "Recent studies demonstrated that melatonin receptor 2 (MT2) protects cardiomyocytes from nitrosative stress injury through the MT2/Notch1/Hes1/RORIα signaling pathway in a mouse myocardial ischemia/reperfusion model." (PMID 34616744, 2021). "The Notch1/Hes1 signaling pathway participates in the melatonin-mediated cardioprotective effects demonstrated in both in vivo and in vitro models of myocardial ischemia–reperfusion injury." (PMID 27630117, 2016). "Recently, Yu and colleagues demonstrated that melatonin protected against myocardial ischemia–reperfusion injury via the modulation of the Notch1/Hes1 signaling pathway." (PMID 27630117, 2016). "NOTCH1 is reported to promote proliferation and differentiation of cardiac progenitor cells and to reduce oxidative stress as well as prevent cardiac fibrosis in myocardial ischemia." (PMID 40725010, 2025). "Consistent with our results, Nogo-B was earlier found to be upregulated in the heart following myocardial ischemia, and Nogo-B overexpression in endothelial cells improved neovascularization, reduced scar size and improved cardiac function post-MI through Notch1 signaling." (PMID 39009944, 2024). "In addition, in the Langendorff cardiac perfusion model, the activated Notch1 signal restores cardiac function, reduces lactate dehydrogenase release, and limits infarct size after myocardial ischemia." (PMID 36611931, 2022). "Melatonin exerts beneficial effects on many aspects of AD and may protect against myocardial ischemia via Notch1 signaling regulation." (PMID 27630117, 2016). "Furthermore, in langendorff heart perfusion model, activated Notch1 signaling restored cardiac function, decreased lactate dehydrogenase release and limited infarct size after myocardial ischemia." (PMID 24098939, 2013). "Next, we observed the effect of Notch1 signaling on cell apoptosis after myocardial ischemia." (PMID 24098939, 2013). "Notch1 acts as an endogenous myocardial protective factor through the RISK/SAFE/HIF-1 alpha signaling, which reduces myocardial intracellular reactive oxygen species (ROS), enhances the myocardiocytes vitality, and significantly reduces the myocardial ischemia reperfusion injury." (PMID 35265142, 2022).
renal carcinoma (11 papers, 2013 to 2022). A carcinoma arising from the epithelium of the renal parenchyma or the renal pelvis. "Indeed, Aparicio’s and Buzkulak’s research demonstrated that Notch 1 protein levels increase in renal carcinoma in association with clinical staging." (PMID 23659326, 2013). "Specific inhibition of Notch1 in renal carcinoma cells reduced the level of B-cell lymphoma/leukemia-2 (BC1-2) proteib and increased apoptosis." (PMID 35096263, 2022). "All these results supported the conclusion that TEB cells promote renal cancer metastasis via inducing the IL-1β/HIF-2α/Notch1 signals." (PMID 32123166, 2020). "Therefore, it can prove that the abnormal Notch1 signaling pathway is involved in the pathogenesis of early renal cancer." (PMID 35096263, 2022). "In addition, we found an elevated expression of KRT6B, a member of the extracellular matrix protein family known to interact with Notch1 and contribute to renal carcinoma progression." (PMID 31092844, 2019). "Thus, the expression of Notch 1 and HES-1 proteins was more readily decreased in the Marimastat treated renal carcinomas than in those treated by DAPT." (PMID 23659326, 2013).
rheumatoid arthritis (11 papers, 2020 to 2024). A chronic, systemic autoimmune disorder characterized by inflammation in the synovial membranes and articular surfaces. "In synovial fibroblasts of patients with rheumatoid arthritis Tumor Necrosis Factor (TNF) drives the expression of Jagged-2, Notch-1, and Notch-4, along with a hallmark of Notch activation, the Notch intracellular domain (NICD) nuclear translocation." (PMID 38314334, 2024). "In an animal model of rheumatoid arthritis, Notch1 and its downstream target molecule Hes are highly expressed in macrophages, and the administration of Notch inhibitors reduces the inflammatory infiltration and the expression of inflammatory factors." (PMID 38832986, 2024). "This study supports Notch-1 signaling as a therapeutic target to combat infection in autoimmune diseases such as Crohn’s disease and Rheumatoid Arthritis." (PMID 32635645, 2020). "Using KO simulations, we identified NFkB, JAK1/JAK2, and ERK1/Notch1 as potential targets that could selectively suppress proinflammatory macrophages and GSK3B as a promising target that could promote anti-inflammatory macrophages in rheumatoid arthritis." (PMID 38272919, 2024).
Richter syndrome (11 papers, 2012 to 2025). Transformation of chronic lymphocytic leukemia into aggressive non-Hodgkin's lymphoma, usually diffuse large B-cell lymphoma (immunoblastic or centroblastic variant). "This subtype of CLL patients has a higher likelihood of developing Richter’s syndrome, and when mutations in NOTCH1 co-occur with trisomy 12, the prognosis is very unfavorable." (PMID 36612190, 2022). "Notch1 activation mutations contribute to treatment resistance in DLBCL, especially in Richter syndrome, impacting disease invasiveness and chemotherapy resistance." (PMID 39951437, 2025). "Whereas, NOTCH1 mutations in CLL lead to the accumulation of the NOTCH1 intracellular domain (NICD), enhancing BCR signaling response, inducing a more aggressive disease, and favoring Richter’s syndrome transformation." (PMID 33669945, 2021). "Recent studies have also shown that mutations of NOTCH1 promoted the release and stabilization of ICN, which in turn excessively inhibited CLL cell apoptosis and to a greater extent, led to aggressive progression to Richter’s syndrome." (PMID 25633905, 2015). "In addition, the risk for patients with trisomy 12 for transformation into clonally related Richter’s syndrome is 10-times higher for NOTCH1-mutated patients compared to wild-type, suggesting that Notch1 signaling drives genomic instability and clonal evolution." (PMID 36266281, 2022).
astrocytoma (10 papers, 2013 to 2024). "Meanwhile, other molecular biomarkers indicating worse outcome in IDH‐mutant astrocytoma, including NOTCH1 mutations and incomplete resections in oligocytoma and PIK3R1 mutations, RB1 mutations and CDK4 mutations and amplifications in astrocytoma." (PMID 37667984, 2023). "We also found that alterations in PIK3R1, Notch1, and Mycn are associated with the overall survival of molecular WHO Grade 4 astrocytoma." (PMID 38970209, 2024). "The results of univariate regression analysis suggested that alterations in PIK3R1 (p = 0.033), Notch1 (p = 0.027), and Mycn (p = 0.027) may be associated with shorter OS in molecular WHO Grade 4 astrocytoma." (PMID 37667984, 2023). "Variations of BCOR, MYCN, NOTCH1, and PIK3R1 and positive immunohistochemistry for S100 showed statistically significant results in univariate survival analysis in WHO grade 4 astrocytoma." (PMID 38970209, 2024). "PIK3R1, Notch1, and Mycn alterations might affect the overall survival of molecular WHO Grade 4 astrocytomas." (PMID 37667984, 2023). "RBPJ aberrations were mutually exclusive with NOTCH1 mutations and were not present in IDH mutant or IDH wild-type astrocytomas." (PMID 30417117, 2018). "The finding of PIK3R1, Notch1, and Mycn alterations as negative prognostic factors in molecular WHO Grade 4 astrocytomas may shed light on understanding the biobehavioral progression and also potential targeted therapies for this specific subset of astrocytomas." (PMID 37667984, 2023).
autoimmune disease (10 papers, 2018 to 2025). A disorder resulting from loss of function or tissue destruction of an organ or multiple organs, arising from humoral or cellular immune responses of the individual to their own tissue constituents. "Notch1 is the key molecule in the regulation of T cells, and its role in autoimmune diseases remains obscure." (PMID 34431214, 2021). "Similarly, NOTCH1 regulates cellular differentiation and inflammatory cytokine secretion in multiple pathological contexts, including cancer and autoimmune diseases." (PMID 40799650, 2025). "A better understanding of the detailed mechanisms of the transcriptional regulation of Notch1 in T cells may provide opportunities for further progress in research into autoimmune diseases and immunomodulatory therapies." (PMID 36593298, 2023). "The study clearly supported the role of Notch-1 signaling in MAP infection in autoimmune diseases." (PMID 33072191, 2020). "Therefore, we believe that DAPT has broad prospect and Notch 1 inhibitor may become a novel prospective therapeutic agent for epilepsy or other central autoimmune diseases also with systemic‐central inflammation crosstalk." (PMID 39136073, 2024).